ING4 (inhibitor of growth family member 4)
Description:
Component of HBO1 complexes, which specifically mediate acetylation of histone H3 at 'Lys-14' (H3K14ac), and have reduced activity toward histone H4. Through chromatin acetylation it may function in DNA replication. May inhibit tumor progression by modulating the transcriptional output of signaling pathways which regulate cell proliferation. Can suppress brain tumor angiogenesis through transcriptional repression of RELA/NFKB3 target genes when complexed with RELA. May also specifically suppress loss of contact inhibition elicited by activated oncogenes such as MYC. Represses hypoxia inducible factor's (HIF) activity by interacting with HIF prolyl hydroxylase 2 (EGLN1). Can enhance apoptosis induced by serum starvation in mammary epithelial cell line HC11 (By similarity).
Synonyms: My036; p29ING4
Tractability: PROTAC: ubiquitination databases record sites on it; its protein half-life has been measured.
Gene: Protein-coding gene on chromosome 12 (6,650,300 to 6,663,148, reverse strand). Ensembl gene ENSG00000111653.
Subcellular location: Nucleus
Subcellular location (Human Protein Atlas): Nucleoplasm
Pathways (Reactome):
Chromatin organization: HATs acetylate histones
Gene Ontology:
Molecular function: histone H3K14 acetyltransferase activity; histone H3K4me3 reader activity; histone H4K12 acetyltransferase activity; histone H4K16 acetyltransferase activity; histone H4K5 acetyltransferase activity; histone H4K8 acetyltransferase activity; protein binding; transcription coactivator activity
Biological process: DNA replication-dependent chromatin disassembly; negative regulation of cell population proliferation; negative regulation of DNA-templated transcription; negative regulation of growth; protein acetylation; regulation of cell cycle; regulation of cell cycle G2/M phase transition; regulation of cell growth; regulation of DNA biosynthetic process; regulation of DNA-templated transcription; positive regulation of apoptotic process; chromatin remodeling; positive regulation of DNA-templated transcription
Cellular component: histone acetyltransferase complex; nucleoplasm; nucleus
Genetic constraint (gnomAD): Loss-of-function variants: 22 observed, 29.63 expected, observed/expected ratio (o/e) 0.74, 90% interval 0.53 to 1.06. The upper end of that interval is the gene's LOEUF score, 1.06, which puts it in group 4 of 6, group 1 being the genes least tolerant of losing a copy. Missense variants: 228 observed, 302.79 expected, observed/expected ratio (o/e) 0.75, 90% interval 0.68 to 0.84. Synonymous variants: 81 observed, 101.64 expected, observed/expected ratio (o/e) 0.8, 90% interval 0.67 to 0.96.
Homologues: Orthologues: pig ING4 (99% identical), chimpanzee ING4 (99% identical), rabbit ING4 (99% identical), mouse Ing4 (99% identical), macaque ING4 (98% identical), rat Ing4 (98% identical), guinea pig ING4 (98% identical), tropical clawed frog ing4 (85% identical), zebrafish ing4 (82% identical), Drosophila melanogaster CG7379 (35% identical), Caenorhabditis elegans lsy-13 (25% identical). Paralogues in human: ING5 (71% identical), ING3 (38% identical), ING1 (37% identical), ING2 (37% identical).
Diseases named in the same sentence as ING4 in open-access papers:
ING4 is named in the same sentence as 64 diseases in open-access papers, as found by Europe PMC text mining. Sharing a sentence is not in itself a finding about the gene and the disease. The quoted sentences say what the papers report.
breast carcinoma (15 papers, 2012 to 2025). "To better characterize the TIME associated with metastatic ING4-deficient breast cancer, we sought to utilize an immune-competent mouse model of ER- breast cancer." (PMID 38968186, 2024). "In this study, we investigated the TIME in ING4-deficient breast cancer by characterizing patient samples and mouse mammary tumors." (PMID 38968186, 2024). "The study results provide the first evidence that ING4-deficient tumors harbor an immune-evasive tumor microenvironment that contributes to metastatic progression and poor patient survival in breast cancer." (PMID 38968186, 2024). "Further characterization of TAMs in Ing4-deleted mammary tumors will be necessary to ascertain the phenotypes and functional contribution of TAMs in ING4-deficient breast cancer progression." (PMID 38968186, 2024). "In breast cancer, NF-kB activation was prevalent among ING4-deficient tumors, associated with advanced stage, lymph node positivity, and poor patient survival." (PMID 38968186, 2024). "The immune markers associated with Ing4-deleted mouse mammary tumors were evaluated for patient survival using the METABRIC breast cancer gene expression dataset." (PMID 38968186, 2024). "The METABRIC data analyses showed that low expression of GZMB was significantly associated with poor patient survival, as was ING4-low expression, in the basal subtype of breast cancer." (PMID 38968186, 2024). "Intriguingly, the TIME of Ing4-deleted mouse mammary tumors consisted of increased tumor-associated macrophages (TAMs) and decreased GzmB+CD4+ T cells." (PMID 38968186, 2024). "Experiments demonstrate that human breast cancer cells T47D, which are deficient in ING4, display contact inhibition." (PMID 30643005, 2019). "miR-650 expression altered through its complementary binding to the 3′-UTR of ING4 is found to be associated with numerous cancer types, including gastric, chronic lymphocytic leukemia, lung, hepatocellular, osteosarcoma, and breast cancers." (PMID 30643005, 2019). "The use of replication-deficient Ad vectors to express ING4 gene demonstrated improved therapeutic efficacy and growth suppression of lung, pancreatic, and breast carcinoma tumor xenografts." (PMID 27349517, 2016). "Other members of the ING family, and in particular ING4, have also been reported to be down-regulated in breast cancers with a dominant mutant allele of the ING4 gene promoting tumor growth." (PMID 26306560, 2015). "We showed that low ING4 mRNA expression was associated with reduced disease-free survival in breast cancer patients in two independent datasets." (PMID 23056468, 2012). "Consistent with this idea, many genes in the ING4/NF-κB gene signature have been implicated to have a role in aggressive breast cancer." (PMID 23056468, 2012). "Although the statistical significance could not be reached due to the small cohort size, the trend showed that Ing4-deleted tumors were more metastatic, consistent with the hypothesis that ING4 deficiencies promote metastatic progression in breast cancer." (PMID 38968186, 2024). "Low expression of the Granzyme B gene (GZMB) in combination with ING4-deficiencies was significantly associated with poor patient survival in the basal subtype of breast cancer, supportive of the clinical significance of granzyme-B-positive immune cell depletion in ING4-deficient tumors." (PMID 38968186, 2024). "Taken together, the study results present a novel mechanism of ING4-driven tumor-immune modulation and may offer potential opportunities for therapeutic intervention harnessing CD4 CTLs in ING4-deficient breast cancer." (PMID 38968186, 2024).
breast carcinoma (continued). "Moreover, low ING4 expression or high expression of the gene signature composed of a subset of ING4-repressed NF-κB-target genes was associated with reduced disease-free survival in breast cancer patients." (PMID 23056468, 2012). "Using other NF-κB activating agents such as TNF and surveying more extensive NF-κB-target gene sets may help to refine the ING4/NF-κB gene signature associated with aggressive breast cancer." (PMID 23056468, 2012). "Interestingly, the deletion of ING4 gene was associated with HER2 status in breast cancer." (PMID 33469513, 2020). "We also analyzed an independent dataset, NKI295, and found that low ING4 expression was associated with reduced disease-free survival (HR = 1.55, 95% CI 1.03–2.21, log-rank P = 0.036), validating that low ING4 expression is associated with reduced disease survival in breast cancer." (PMID 23056468, 2012). "In breast cancer, ING4 is deleted and/or downregulated in up to 34% of tumors correlating with advanced stage, lymph node positivity, and poor patient outcomes." (PMID 38968186, 2024). "ING4 has been shown to inhibit NF-kB in various cancer types including breast cancer, melanoma, glioma, squamous cell carcinoma, and hepatocellular carcinoma." (PMID 38968186, 2024). "In summary, the breast tumor IHC results showed that ING4-low/pp65-high tumors were associated with CD8+ T cells and lymph node metastasis in ER- breast cancer." (PMID 38968186, 2024). "These supported the tumor suppressive roles for granzyme B and ING4 in the basal subtype breast cancer." (PMID 38968186, 2024). "The results presented in this study provided the first evidence that ING4-deficient tumors harbor a TIME that contributes to metastatic progression and poor patient survival outcomes in breast cancer." (PMID 38968186, 2024). "Expression of a dominant negative ING4 mutant increased mammary tumor metastasis in mice, corroborating the tumor suppressive function of ING4 in breast cancer." (PMID 38968186, 2024). "In mice, Ing4-deleted mammary tumors had a growth rate comparable to Ing4-intact tumors but showed increased tumor penetrance and metastasis." (PMID 38968186, 2024). "To characterize the immune components in Ing4-deleted mammary tumors, we employed flow cytometry and evaluated myeloid and lymphoid cell populations within the tumors." (PMID 38968186, 2024). "For instance, in mouse mammary glands, the overexpression of a C-terminal truncated ING4, that lacks the PHD motif, resulted in mammary hyperplasia, while co-expression of the mutant ING4 along with MYC oncogene-induced metastasis of breast cancer." (PMID 34685579, 2021). "ING4 interacts with the NFκB pathway to suppress angiogenesis in glioma, colorectal, and breast cancers." (PMID 33925563, 2021). "In breast cancer patients with the larger the tumor, the higher the stage, and the lower the expression of ING4 were more prone to lymph node metastasis." (PMID 33469513, 2020). "Previous study had shown that low expression of ING4 reduced the efficacy of tamoxifen in breast cancer, by inhibiting ER activity in hormone-dependent breast cancer." (PMID 33469513, 2020). "Expression of a dominant negative mutant of ING4 has been considered to co-operate with the MYC oncogene to form mammary tumors." (PMID 30643005, 2019). "ING4/IL-24 gene therapy and radiotherapy suppressed cell proliferation and induced apoptosis in breast cancer cells." (PMID 24377906, 2013). "We have shown that the ING4 gene is deleted in 16.5% of breast tumors, suggesting a tumor suppressive role in a subset of breast cancer." (PMID 23056468, 2012). "Our study constitutes the first report of the clinical consequence of low ING4 expression in breast cancer." (PMID 23056468, 2012).
breast carcinoma (continued). "Our study provides insight into the tumor suppressor function of ING4 in breast cancer and offers a molecular basis to explore the ING4/NF-κB pathway as a potential therapeutic target in order to block disease progression and improve patient survival." (PMID 23056468, 2012). "Subsequently, we showed that ING4 suppressed T47D breast cancer cell growth in soft agar and MYC-initiated mammary hyperplasia in a mouse model, providing evidence for the ING4 tumor suppressor function in breast cancer." (PMID 23056468, 2012). "Taken together with the luciferase reporter assay results, we concluded that ING4 attenuated NF-κB-mediated gene transcription in T47D breast cancer cells." (PMID 23056468, 2012). "In this study, we showed that 34% of breast tumors expressed relatively low levels of the ING4 protein, implicating a tumor suppressive role for ING4 in a larger subset of breast cancer." (PMID 23056468, 2012). "ING4-low tumors were comparably prevalent between invasive ductal carcinoma and lobular carcinoma (32% vs 30%), suggesting a tumor suppressive role of ING4 in breast cancers rising from both ductal and lobular structures." (PMID 23056468, 2012). "Here we present evidence that the Inhibitor of Growth 4 (ING4) tumor suppressor negatively regulates NF-κB in breast cancer." (PMID 23056468, 2012). "T47D cells are a breast cancer cell line that contains only one copy of the ING4 gene due to a defined deletion on chromosome 12, providing an example of “ING4 low” expressing cells." (PMID 23056468, 2012). "Recently, we reported that 16.5% of breast tumors harbored an ING4 gene deletion, suggesting a tumor suppressive role of ING4 in at least a subset of breast cancer." (PMID 23056468, 2012). "All 6 DCIS cases showed +3 score for ING4, indicating that this non-invasive form of breast cancer expressed ING4 at a level well detectable by IHC." (PMID 23056468, 2012). "Supportive of the functional contribution of the TIME in ING4-deficient tumor progression, low GZMB gene expression together with low ING4 expression was significantly associated with poor patient survival outcomes in the basal subtype of breast cancer." (PMID 38968186, 2024). "This association between the ING4-low/NF-kB-high status and lymph node positivity was more pronounced in estrogen receptor-negative (ER-) breast cancer (75% vs 25–29%)." (PMID 38968186, 2024). "Ing4-deleted mouse mammary tumors contained a significantly reduced number of GzmB+CD4+ T cells." (PMID 38968186, 2024). "Additionally, JFK-mediated ING4 proteasomal degradation promotes angiogenesis and metastasis of breast cancer." (PMID 34336836, 2021). "At the same time, the expression of ING4 is negatively correlated with the histological grade of breast cancer, and overexpressed ING4 can inhibit the formation of microvessel in tumor tissue to inhibit the occurrence and development of breast cancer and improve the disease-free survival rate." (PMID 33469513, 2020). "The expression of ING4 was negatively correlated with histological grade of breast cancer." (PMID 33469513, 2020). "Studies has shown that compared with benign epithelium, the nuclear expression of ING4 is decreased, and the cytoplasmic expression of ING4 is positively correlated with the expression of HER2 in breast cancer, which suggests that ING4 plays a role in the pathogenesis of breast cancer." (PMID 33469513, 2020). "Ad-ING4 gene transfer significantly induces tumor growth suppression and apoptosis and reduces tumor vessels and microvessel density in human osteosarcoma, lung, pancreatic, and breast carcinomas." (PMID 30643005, 2019). "Whether the tumor suppressor function of ING4 involves the repression of NF-κB-target genes in other cancer types including breast cancer is currently unknown." (PMID 23056468, 2012). "In addition, ING4 suppressed PMA-induced cell invasion and NF-κB-target gene expression in T47D cells, indicating that ING4 inhibited NF-κB activity in breast cancer cells." (PMID 23056468, 2012).
breast carcinoma (continued). "Tumors with low ING4 expression were frequently large in size, high grade, and lymph node positive, suggesting that down-regulation of ING4 may contribute to breast cancer progression." (PMID 23056468, 2012). "Consequently, down-regulation of ING4 leads to activation of NF-κB, contributing to tumor progression and reduced disease-free patient survival in breast cancer." (PMID 23056468, 2012). "We tested whether ING4 protein expression levels affected phosphorylation of p65/RelA in breast cancer cell lines in vitro." (PMID 23056468, 2012). "We conclude that ING4 negatively regulates NF-κB in breast cancer." (PMID 23056468, 2012). "Here, we present evidence that ING4 inhibits NF-κB in breast cancer cells and propose that down-regulation of ING4 is one of the molecular events that leads to NF-κB activation, promoting tumor progression and resulting in reduced patient survival in breast cancer." (PMID 23056468, 2012). "Taken together, we conclude that ING4 negatively regulates NF-κB in breast cancer." (PMID 23056468, 2012). "Consequently, down-regulation of ING4 results in NF-κB activation, leading to disease progression and poor patient outcome in breast cancer." (PMID 23056468, 2012). "Together, these results suggested that down-regulation of ING4 may foster phospho-activation of p65/RelA, resulting in aggressive breast cancer." (PMID 23056468, 2012). "Gene deletion or reduced expression of ING4 has been reported in various cancers including glioma, breast cancer, head and neck carcinoma, melanoma, hepatocellular carcinoma, gastric carcinoma, colon cancer, and lung cancer, implicating a tumor suppressive role of ING4 in diverse tissue types." (PMID 23056468, 2012). "We found that low ING4 expression correlated with high levels of phosphorylated p65/RelA (p-p65/RelA), an activated form of NF-κB, in breast tumors, suggesting that down-regulation of ING4 may foster NF-κB activation in breast cancer." (PMID 23056468, 2012). "In agreement with the Ing4−/− model, small interfering RNA-mediated silencing of ING4 prevents normal cell cycle progression of human breast cancer MCF7 cells, marked with an accumulation in the G2/M phase of the cell cycle." (PMID 33925563, 2021). "The reduced expression of tumor suppressor ING4 has been reported in various malignancies, and down-regulation of ING4 is correlated with increased tumor metastasis, advanced TMN stages and poor patients survival in melanoma, gastric cancer and breast cancer." (PMID 27806345, 2016). "Consistent with the inverse relationship between ING4 and p-p65/RelA levels in breast tumors, over-expression of ING4 resulted in the inhibition of p65/RelA phosphorylation in the T47D and MCF7 breast cancer cell lines." (PMID 23056468, 2012). "We overexpressed ING4 in T47D and MCF7 breast cancer cells, treated cells with PMA to induce phosphorylation and nuclear localization of p65/RelA, and blotted for p-p65/RelA (Ser536), another activated form of p65/RelA." (PMID 23056468, 2012). "Conversely, ectopic expression of ING4 inhibited p65/RelA phosphorylation in T47D and MCF7 breast cancer cells." (PMID 23056468, 2012). "In conclusion, we found the unique tumor immune composition resulting from the absence of Ing4 in mammary tumors, consisting of decreased CD4 CTLs indicative of an immune-evasive TME, correlating with increased penetrance (fitness for survival) and metastasis." (PMID 38968186, 2024). "Enhanced tumor suppression was shown by nonreplicating bicistronic Ad vector expressing both ING4 and IL-24 genes employed for treatment of human non-small cell lung cancer, breast cancer, and hepatocarcinoma subcutaneous tumor xenografts." (PMID 27349517, 2016). "Interestingly, ING4 and ING5 are also required for proliferation of breast cancer cells, supporting the hypothesis that ING proteins play pleiotropic functions in eukaryotic cells." (PMID 33925563, 2021).